CXCL12 (C-X-C motif chemokine ligand 12)
Diseases named in the same sentence as CXCL12 in open-access papers (continued):
Sharing a sentence is not in itself a finding about the gene and the disease.
tumor (continued). "The overexpression of POU1F1 in cancer cells increases CXCL12 chemokine secretion, which promotes monocyte recruitment to the tumor microenvironment and macrophage transformation into CD163+ macrophages." (PMID 36373483, 2023). "Research addressing the relationship between CXCL12 and tumor suppression shows that CXCL12 plays a role as a tumor-suppressive cellular brake." (PMID 37966614, 2023). "CXCL12 has been demonstrated to promote tumor cell proliferation and survival and can synergize with VEGF to induce neoangiogenesis in vivo." (PMID 38022679, 2023). "The CXCL12/CXCR4 axis is a key mediator of tumor spread, site-specific metastasis, and patient survival." (PMID 37227446, 2023). "Both stromal- and tumor-derived CXCL12 can directly stimulate the growth and proliferation of tumor cells." (PMID 37497001, 2023). "Evaluation of changes within the tumor microenvironment induced by CXCL12 inhibition with NOX-A12 by comparing pre- and post-treatment biopsy specimens.Safety and tolerability of NOX-A12 plus pembrolizumab." (PMID 37035150, 2023). "CXCL12 can attract immune cells to the tumor microenvironment, potentially enhancing anti-tumor responses and improving the prognosis." (PMID 37895012, 2023). "Compounds aiming to block the angiogenic and chemotactic effect of CXCL12 to prevent tumor growth and metastasis are evaluated in pre-clinical and clinical research." (PMID 36725964, 2023). "CXCL12 is a critical modulator in the tumor microenvironment, influencing various oncogenic processes including angiogenesis, osteoclast-genesis, tumor cell immigration and adherence to stromal cells." (PMID 37798791, 2023). "Activated RhoA and RhoC led to CXCR4-mediated migration of T-ALL cell lines to CXCL12, triggering leukemic tumor cells infiltration." (PMID 37497001, 2023). "Molecular analysis revealed that this proinflammatory signaling increased tumor cell secretion of CXCL12 as well as DC expression of CXCR4 (i.e., CXCL12 receptor), indicating a role for this pathway in the results observed." (PMID 38106674, 2023). "Expression of CXCL12 in tumor cells correlated positively with the degree of keratinization, whereas it correlated negatively with histological grade." (PMID 36300800, 2023). "Among all subjects, the progression-free survival and overall survival were significantly prolonged in cancer patients with low tumor expression of CXCL12 compared to patients with high tumor expression." (PMID 37227446, 2023). "The protective effect of CXCL12 against tumor was significantly attenuated when T cells were intervened with AMD3100 alone prior to co-culture." (PMID 38001512, 2023). "Compared to CXCR4, which showed a smaller difference in SVs, CXCL12 displayed a significant difference in most splicing events in normal versus tumor tissues." (PMID 37198402, 2023). "At last, to investigate the effect of blocking CXCL12 on tumor growth in vivo, we established tumor models." (PMID 38001512, 2023). "In this study, we aimed to clarify the biological and clinical significance of CXCL12 in the tumor microenvironment of OSCCs." (PMID 36300800, 2023). "Expression of CXCL12 is highest in TAM_c1 subset, supporting revascularization of ischemic tissue and tumor growth." (PMID 38044943, 2023). "Its functional receptor, CXCR4, is highly expressed in various human malignancies, and numerous studies have shown that the CXCL12/CXCR4 axis promotes tumor growth, angiogenesis, invasion, and metastasis." (PMID 36300800, 2023). "CAFs are a great part of the tumor stroma, and CXCL12 secreted by CAFs plays an important role in ‘protecting’ tumor cells from immune attack and keeping T cells out of the tumor microenvironment." (PMID 37509328, 2023). "CAF-enriched primary tumor stroma can mimic the CXCL12-rich bone metastatic niche and can thus be used to help identify potentially metastatic cancer cells." (PMID 37496657, 2023).
tumor (continued). "To more precisely determine the distribution of CXCL12 expression within the tumor microenvironment, we used immunohistochemistry to assess the relationship between CXCL12 expression and expression of the CAF marker α‐SMA within OSCC specimens." (PMID 36300800, 2023). "Cancer-associated immune cells are recruited in the tumor niche in response to several chemokines and cytokines released from tumor cells, such as CCL2, IL-8, CXCL12, and CCL5." (PMID 37592292, 2023). "As demonstrated by our findings, ECM-modulating genes, such as MMP2 and MMP14, were clearly upregulated in the CAFs, and CAFs were found to secrete PDGFRA and CXCL12, which promote tumor progression, further validate the accuracy of CAF classification." (PMID 37565899, 2023). "Nevertheless, when LECs express CXCR4 that later interacts with CXCL12 found on tumoral cells, tumor lymphangiogenesis and lymphatic metastasis are promoted." (PMID 37744339, 2023). "In this study, we found that CXCL12 is expressed in tumor, stromal, and muscle cells within primary OSCC tissues." (PMID 36300800, 2023). "CAFs also secrete a series of factors and proteins, such as CXCL12 and Tenascin C, which promote tumor metastasis and densify the tumor matrix to build a barrier to prevent drug penetration." (PMID 36762192, 2023). "CXCR4 was highly expressed in cluster 7 ECs, and this chemokine receptor binds to CXCL12-expressing TAMs and promotes tumor metastasis and progression, indicating the pro-cancer properties of this cell cluster." (PMID 37533434, 2023). "Many factors are thought to play a role in attracting tumor cells to the bone microenvironment, including the CXCL12/CXCR4 signaling axis." (PMID 37446097, 2023). "CXCL12 is a driving factor for tumor cell and enhances vascular permeability, which enables tumor cells to escape from the primary site to other distant organ." (PMID 37978384, 2023). "Grade 1 tumors were characterized by focal tumor cell proliferation, collective migration, and greater degrees of keratinization, as well as abundant CXCL12 expression." (PMID 36300800, 2023). "In primary tumors, PCa-derived CXCL16 recruits CXCR6-expressing MSCs which upregulate PCa CXCR4 expression, induce EMT markers via CXCL12 secretion, and promote tumor growth in vivo in a subcutaneous model." (PMID 37025604, 2023). "CXCL12 overexpressed in senescent CRC tumor cells inhibits CD8+ T lymphocyte infiltration by reducing the production of T cell-attracting chemokines." (PMID 37175861, 2023). "A known pathway for the induction of CXCL12-mediated anticancer drug resistance is the activation of the PI3K-Akt-mTOR system in tumor cells." (PMID 37264057, 2023). "Tregs are a crucial therapeutic target in the TME, they can be recruited to the TME by macrophages and tumor-derived factors such as CXCL12, CCL17 CCL22 and CCL1, thus suppressing the activation of T cells." (PMID 37656220, 2023). "The interaction of the receptor CD184/CXCR4 with its ligand SDF-1(also called CXCL12), enhances the interaction of CSCs with the tumor microenvironment." (PMID 36864434, 2023). "CXCL12, mainly secreted by activated CAFs in desmoplastic tumors, maintained the tumor-promoting phenotype of CAFs, which accelerated tumor growth and metastasis." (PMID 36762192, 2023). "CXCL12 has been revealed to participate in the development of chemotherapy resistance in various tumours." (PMID 38057830, 2023). "Previous evidence suggests that this local production of CXCL12 promotes cancer progression by stimulating tumor cell proliferation, angiogenesis, and epithelial-mesenchymal transition (EMT)." (PMID 37227446, 2023). "It is reported that the recruitment of endothelial progenitor cells (EPCs) was mediated by CAF-derived CXCL12, which promoted angiogenesis in BC, and CXCL12 secreted by CAF also directly stimulated tumor growth." (PMID 37784082, 2023).
tumor (continued). "In multivariate analysis, the increased expression level of CXCL12 was a significant predicting factor for progression-free survival and overall survival after adjustment for gender, age, pathological stage, tumor histology, and adjuvant chemotherapy." (PMID 37227446, 2023). "Immunohistochemical analysis showed that in grade 1 primary OSCCs, CXCL12 is expressed in both tumor cells and muscle cells." (PMID 36300800, 2023). "This seems to be guided by chemokines such as CXCL12, CXCL10 and CCL2, produced by various cell types such as tumor cells, and tumor-associated macrophages and fibroblasts." (PMID 36766797, 2023). "The TGF-β and CXCL12 expression levels in tumour-bearing mice were significantly higher than those in normal mice, explaining metastasis regarding tumour cells to multiple organs." (PMID 37162544, 2023). "The downregulation of mir-101 in CAF exosomes releases their tumor-promoting effects through CXCL12." (PMID 37046676, 2023). "We found that CXCL12 is abundantly expressed in fibroblasts within HNSCC tumors, while lower levels of CXCL12 expression were detected in the tumor cells and endothelial cells." (PMID 36300800, 2023). "PTX3, CCL2, and CXCL12 are stroma-derived factors that increase the proliferation rate of mutant desmoid tumor cells." (PMID 37377751, 2023). "As a result of this study, high CXCL12 tumor expression (CXCL12 histoscore) was shown to correlate with better patient survival (p = 0.040)." (PMID 37966614, 2023). "Here, the authors indicate that eliminating CXCL12 expression on afferent lymphatics or blocking CXCR4 on T cells led to retention of T cells at the tumor site and better tumor control." (PMID 37662908, 2023). "Previous reports using murine models have shown that TKIs prompt tumor cells to release chemotactic factors (CXCL12 and HMGB-1) or induce immunogenic cell death, resulting in robust immune cell infiltration and tumor clearance." (PMID 36839733, 2023). "This receptor mediates homing of tumor cells to specific organs expressing the ligand CXCL12 and plays an important role in tumor growth, invasion, metastasis, and angiogenesis." (PMID 37373500, 2023). "High levels of CXCL12 in the tumor can attract CXCR4-expressing immune cells, fibroblasts and endothelial cells to the tumor site further promote tumor growth." (PMID 38022679, 2023). "In a similar way, CXCL12 supports neoangiogenesis while inhibiting endothelial cell apoptosis by binding the receptor CXCR4 present on tumor vessels, or indirectly stimulating leukocyte recruitment." (PMID 36980182, 2023). "E5 blocked CXCL12-mediated endothelial progenitor cell recruitment and slowed tumor angiogenesis by inhibiting AKT and ERK pathways." (PMID 37497001, 2023). "Grade 1 tumors without invasion of the muscularis propria had high neoplastic cell content, and a majority of the tumor area was positive for CXCL12." (PMID 36300800, 2023). "As well as modulating the ECM, CAFs can directly promote tumor progression by secreting CXCL12 and VEGF-A, which promote angiogenesis; however, the proangiogenic function of CAF is influenced by RT." (PMID 37607935, 2023). "CXCL12 can be produced by hyperCAF, the binding of CXCL12 to tumor cells can inhibit tumor cell apoptosis and change the characteristics of tumor cell adhesion." (PMID 37719863, 2023). "Using patient samples and an in vivo model, it was demonstrated that osteosarcomas can epigenetically downregulate CXCL12 expression and as such acquire the ability to form metastases and impair cytotoxic T-lymphocyte homing to the tumor site." (PMID 36725964, 2023). "It enhances apoptosis and directly targets CXCL12, significantly impairing its ability to stimulate tumor cell proliferation, sphere formation migration, and invasion." (PMID 37046676, 2023).
tumor (continued). "Reciprocally, the subsequent release of inflammatory cytokines (IL-6, TNF-α, TGFβ and CXCL12) from CAFs causes EMT and a pro-metastatic switch of CRC cells, and it also facilitates tumor formation and lung metastasis." (PMID 36831450, 2023). "Other studies showed that CXCL12 stimulates angiogenesis and reduces tumor cell apoptosis and tumor necrosis in OC." (PMID 37966614, 2023). "Among subjects with high tumor CXCL12 expression, progression-free survival and overall survival were significantly improved in patients treated with adjuvant chemotherapy compared to untreated patients." (PMID 37227446, 2023). "This study further confirmed that CD26+ NF is converted into a pro-tumor iCAF, which recruits bone marrow cells in a CXCL12-dependent manner and enhances tumor cell invasion through the activity of matrix metalloproteinases (MMPs)." (PMID 38273859, 2023). "Regulation of CXCL12 expression by miRNAs can play a significant role in either tumor progression or suppression, dependent on the miRNA type." (PMID 36725964, 2023). "The PTEN loss in PC cells is associated with enhanced expression of CXCL12 and CXCR4 expression and contributes to tumor growth and metastasis." (PMID 38239314, 2023). "CAFs secreted CXCL12/SDF-1, which contributes to tumor growth and anti-apoptosis in cancer cells via CXCR4." (PMID 37005661, 2023). "The CXCL-12/CXCR4 axis indirectly contributes to the sequestration of cytotoxic T lymphocytes away from the tumor site, leading to reduced infiltration of CTLs." (PMID 37511431, 2023). "The secretion of CXCL12 by caf_C1_scissor induces immunosuppressive cell infiltration, CXCL12 attracts anti-inflammatory M2-like macrophage infiltration, and CXCL12 promotes tumor cell proliferation angiogenesis and metastasis." (PMID 37091977, 2023). "In the literature, CAF-derived CXCL12 has been described to coat cancer cells, whereas immunohistochemical approaches of most studies indicate tumor cells as the primary source of CXCL12." (PMID 37966614, 2023). "The CX chemokine receptor 7 (CXCR7) recognizes its ligand CXCL12, and affects cell adhesion, viability, and tumor growth." (PMID 37635248, 2023). "By binding TNC to CXCL12, it was recently shown that tumor-infiltrating leukocytes are trapped in the stroma, leading to tumor surveillance." (PMID 37834140, 2023). "IM CAFs create an immunosuppressive environment within the tumor through secreting CXCL12, TGF-β, GAS6, IL-6, HGF, GDF15, and FGF5, each of which promote cancer cell invasion, proliferation, and immunosuppression." (PMID 37626931, 2023). "Log-rank statistical analysis corroborated that strong CXCL12 expression, (of both tumor and TICs), was significant prognostic indicators for overall patients’ survival in recurrent cancers (p = 0.004)." (PMID 37966614, 2023). "Tumor cells produce multiple chemokines, including large amounts of CXCL12, which recruits pDCs by binding CXCR4 on pDCs in oral squamous cell carcinoma." (PMID 37817484, 2023). "The mechanism behind this observation is that normal fibroblasts lacking TGFβR2 undergo myofibroblastic differentiation, recapitulating the tumor inductive activity of CAFs that secret various tumor-promoting factors, such as SDF1/CXCL12, FGF, HGF, and BMPs." (PMID 37254126, 2023). "CXCL12 interfered with colon carcinoma and melanoma tumor metastasis via distinct interactions with CXCR4." (PMID 37446102, 2023). "For example, in pancreatic ductal carcinoma, CXCL12 from FAP+ CAFs can wrap tumor cells and inhibit the accumulation of T cells in tumor sites." (PMID 35681617, 2022). "We previously determined that tumor derived growth factors and chemokines, such as SDF1α (CXCL12), TGFβ, and IL1β, promote PI3Kγ-mediated integrin α4β1 conformational changes and adhesion to endothelium in circulating myeloid cells during tumor inflammation." (PMID 35365657, 2022).
tumor (continued). "On the other hand, the induction of CXCL12 expression in the premetastatic niche by factors secreted from the primary tumor is also involved in the homing of tumor cells to the secondary site." (PMID 36497411, 2022). "Possible therapeutic approaches to target the immunosuppressive activity of MDSCs include the inhibition of COX2 to reduce MDSCs recruitment and reduce Arg I expression and blocking CSF-1, CXCL2, or CXCL12 to inhibit trafficking of MDSCs to the tumor." (PMID 36186781, 2022). "CAFs promote functional barriers that contribute to angiogenesis, tumor growth, metastasis, immune suppression, and metabolic reprogramming through the secretion of chemokines such as CXCL12." (PMID 35158804, 2022). "Deserve to be mentioned, NK CD56 bright cells were positively related to ALKBH7, which proved to be correlated with CXCL12 expression in a pancreatic pre-tumor cell model and MARCKS expression in HCC, meanwhile, all of them expressed in various tumor." (PMID 35980268, 2022). "Studies have indicated that the production of chemokine (C-X-C motif) ligand 12 (CXCL12) by FAP+ CAFs within the cancer cell-rich region of a tumor impedes T cell infiltration leading to immunosuppression." (PMID 36263225, 2022). "CXCL12 additionally promotes tumor vascularization by inducing endothelial cell differentiation, proliferation, and morphogenesis via its receptor CXCR7 (also called ACKR3)." (PMID 36568151, 2022). "The functions of CXCR4/CXCL12 extend beyond cell migration and involve the recognition and disposal of unhealthy or tumor cells." (PMID 35565443, 2022). "Investigating a potential interaction of CXCR4/CXCL12 axis with the AR, the most common therapeutic target for systemic therapies, IHC revealed AR expression in EC more affecting tumor areas compared to stromal tissue." (PMID 35717322, 2022). "Induction of CXCL12, CXCR4 and IDO1 in tumours have been associated with accumulation of myeloid derived suppressor cells." (PMID 35355992, 2022). "High CXCR4 expression in tumor cells promotes invasiveness and metastasis, which is exacerbated by high CXCL12 expression in lymph nodes but can be prevented by inhibiting the receptor." (PMID 36164329, 2022). "The CXCL12/CXCR4 axis is crucial signaling for tumor cells cross-talking with the tumor microenvironment that paves a path for tumorigenesis." (PMID 35615089, 2022). "To test our conjecture, by further analysis, we found that CXCR4, a specific receptor for CXCL12, was expressed in T cells and macrophages in tumor tissues." (PMID 36211359, 2022). "In OS6, C25 actively secreted FGF7 and CTGF, which promoted CAF growth and tumor angiogenesis, and CXCL12, which interacted with CXCR4 to block and deplete the T-cell response." (PMID 35664733, 2022). "While this treatment had minimal direct effect on cancer cells, it led to a reduction of serum levels of IL-6 and EGF, known CAF secreted factors and reduced tumour growth was mediated by a reduction of CXCL12 and destruction of ECM." (PMID 35479076, 2022). "TGF-β/SMAD mediates the exosomal secretion of CXCL12/CXCR4 chemokines by CAFs, where CXCL12 promotes cancer malignancy by increasing tumor cell proliferation, migration, and angiogenesis." (PMID 35345849, 2022). "The authors report that neutralization of CXCL12 with an antibody promotes tumor extension to nearby tissues, accelerates angiogenesis and neovascularization, increases VEGF expression, microvascular permeability and increases CXCR7 expression." (PMID 35406582, 2022). "It was observed that activation of CXCR4 by CXCL12 enforced tumor resistance to therapies by decreasing apoptotic signaling." (PMID 36612163, 2022). "CXCR4 and CXCL12 are key to tumor cell migration and directly affect the formation of pre-metastatic niche." (PMID 35965504, 2022). "Tumor expressing high levels of CXCL12 repelled CXCR4-expressing T cells and evaded an anti-tumor response." (PMID 33603130, 2022).